HDGFL2 (HDGF like 2)
Description:
Acts as an epigenetic regulator of myogenesis in cooperation with DPF3a (isoform 2 of DPF3/BAF45C). Associates with the BAF complex via its interaction with DPF3a and HDGFL2-DPF3a activate myogenic genes by increasing chromatin accessibility through recruitment of SMARCA4/BRG1/BAF190A (ATPase subunit of the BAF complex) to myogenic gene promoters. Promotes the repair of DNA double-strand breaks (DSBs) through the homologous recombination pathway by facilitating the recruitment of the DNA endonuclease RBBP8 to the DSBs. Preferentially binds to chromatin regions marked by H3K9me3, H3K27me3 and H3K36me2. Involved in cellular growth control, through the regulation of cyclin D1 expression.
Synonyms: HRP-2; HDGF-2; HDGF2; HDGFRP2; HRP2
Tractability: Small molecule: a structure with a bound ligand is known. PROTAC: UniProt records ubiquitination sites on it; ubiquitination databases record sites on it.
Target class: Reader; Methyl-lysine/arginine binding protein; Epigenetic regulator; PWWP domain
Gene: Protein-coding gene on chromosome 19 (4,472,244 to 4,502,220, forward strand). Ensembl gene ENSG00000167674.
Subcellular location: Nucleus; Cytoplasm
Subcellular location (Human Protein Atlas): Nucleoplasm; Cytosol; Mitochondria
Gene Ontology:
Molecular function: histone H3K27me3 reader activity; histone H3K9me2/3 reader activity; histone reader activity; protein binding
Biological process: DNA repair-dependent chromatin remodeling; muscle cell differentiation; positive regulation of cell growth; positive regulation of double-strand break repair via homologous recombination; chromatin remodeling; skeletal muscle tissue regeneration
Cellular component: nucleoplasm; nucleus; cytoplasm
Genetic constraint (gnomAD): Loss-of-function variants: 33 observed, 60.07 expected, observed/expected ratio (o/e) 0.55, 90% interval 0.41 to 0.74. The synonymous counts are far from expectation, so gnomAD's model fits this gene poorly and the ratio says little. Missense variants: 970 observed, 847.99 expected, observed/expected ratio (o/e) 1.14, 90% interval 1.08 to 1.21. Synonymous variants: 462 observed, 356.6 expected, observed/expected ratio (o/e) 1.3, 90% interval 1.2 to 1.4.
Homologues: Orthologues: chimpanzee HDGFL2 (98% identical), macaque HDGFL2 (95% identical), pig HDGFL2 (87% identical), guinea pig HDGFL2 (85% identical), dog HDGFL2 (84% identical), mouse Hdgfl2 (82% identical), tropical clawed frog hdgfl2 (53% identical), zebrafish hdgfl2 (50% identical). Paralogues in human: PSIP1 (28% identical), HDGFL3 (17% identical), HDGF (15% identical), HDGFL1 (13% identical).
Diseases named in the same sentence as HDGFL2 in open-access papers:
HDGFL2 is named in the same sentence as 56 diseases in open-access papers, as found by Europe PMC text mining. Sharing a sentence is not in itself a finding about the gene and the disease. The quoted sentences say what the papers report.
HIV-1 infection (4 papers, 2012 to 2022). The type species of lentivirus and the etiologic agent of acquired immunodeficiency syndrome (AIDS). "Based on these data, we conclude that inhibition of IN binding to LEDGF/p75 and HDGFL2 in large part accounts for the ability of ALLINIs such as BI-D to retarget integration away from genes when the drugs are present during the early phase of HIV-1 infection." (PMID 36146690, 2022).
infection (116 papers, 2005 to 2026). The state of being infected such as from the introduction of a foreign agent such as serum, vaccine, antigenic substance or organism. "Herein, we mapped integration sites in cells knocked out for LEDGF/p75, HDGFL2, or both factors, which revealed that these two proteins in large part account for ALLINI-mediated integration retargeting during the early phase of infection." (PMID 36146690, 2022).
HDGFL2 also shares sentences with these, for which no sentence is quoted: malaria (368 papers); parasitemia (53); falciparum malaria (36); cancer (8); hepatocellular carcinoma (6); cerebral malaria (4); co-infection (3); leukemia (3); neurodegenerative disease (3); tumor (3); vivax malaria (3); anaemia (2); Coma (2); frontotemporal dementia (2); hepatitis C (2); multiple myeloma (2); osteosarcoma (2); retinopathy (2); rheumatoid arthritis (2); schistosomiasis (2); acute encephalopathies (1); amyotrophic lateral sclerosis (1); autoimmune conditions (1); bacterial infection (1); cervical carcinoma (1); Chagas disease (1); COVID-19 (1); dengue (1); Encephalopathy (1); familial disease (1).
A further 24 diseases each share a sentence with HDGFL2 in 1 paper.